IL6 (interleukin 6)
Diseases named in the same sentence as IL6 in open-access papers (continued):
Sharing a sentence is not in itself a finding about the gene and the disease.
cerebral palsy (18 papers, 2011 to 2024). A group of disorders affecting the development of movement and posture, often accompanied by disturbances of sensation, perception, cognition, and behavior. "Catalase gene and interleukin-6 gene polymorphisms are associated with higher susceptibility to cerebral palsy after neonatal hypoxia-ischemia." (PMID 31275228, 2019). "An increased IL6 in amniotic fluid and cordblood were associated with outcomes such as cerebral palsy and periventricularleukomalacia, respectively." (PMID 31435616, 2019). "In term newborns, catalase gene and interleukin-6 gene polymorphisms are associated with higher susceptibility to cerebral palsy after hypoxia-ischemia." (PMID 31275228, 2019). "Several previous studies have associated elevated IL-6 CSF levels with poor neurological outcome, cerebral palsy, and death in asphyxia." (PMID 29233180, 2017). "Another stipulation is the influence of genetic polymorphisms, such as interleukin-6 (rs1800795), which is associated with the development of cerebral palsy, which may account for racial differences in outcomes of infants seen in other studies." (PMID 34558605, 2022). "Also, increased levels of IL6, IL11, andIL13 have been reported in dried blood samples of infants with cerebral palsy.The results of an animal study showed that the serial injection of synthetic IL6prevents learning disabilities and delays the loss of neurons." (PMID 31435616, 2019).
chronic fatigue syndrome (18 papers, 2015 to 2025). "Other fatigue syndromes, such as myalgic encephalomyelitis (chronic fatigue syndrome) and cytokine release syndrome, are also associated with increased activated T-lymphocytes and pro-inflammatory cytokines such as IL-6, IL-10, and IFN-γ." (PMID 40952384, 2025). "Cytokines found elevated in some chronic fatigue syndrome patients include interferon-γ, IL-6, IL-1, IL-2, and TGF-β." (PMID 36510222, 2022). "Upon EPS, myotubes from individuals with chronic fatigue syndrome have impaired glucose uptake and reduced IL6 secretion compared to healthy myotubes." (PMID 34831227, 2021). "It has also been shown to reduce the expression of the pro-inflammatory cytokines tumor necrosis factor-α (TNF-α) and interleukin (IL)-6 in chronic fatigue syndrome (CFS) patients after six-eight weeks of clinical therapy." (PMID 30658449, 2019). "The study we describe here is the first to examine IL6 levels released specifically from skeletal muscle cells from patients with chronic fatigue syndrome." (PMID 25836975, 2015). "IL6 release was comparable to controls up to 72h after initiation of differentiation but was significantly decreased in the day 7 chronic fatigue syndrome myotube cultures both before and during contraction." (PMID 25836975, 2015). "The levels of IL-6 are raised in B19-infected patients with chronic fatigue syndrome." (PMID 27902343, 2016). "Patients with chronic fatigue syndrome/myalgic encephalitis show increases in both IL-1β and IL-6." (PMID 26469939, 2015). "Interestingly, plasma IL-6 was reduced in UC patients and chronic fatigue syndrome." (PMID 28555037, 2017). "Furthermore, TJ-41 may inhibit Tumor Necrosis Factor-α (TNF-α), Interleukin-6 (IL-6), IL-10, Transforming Growth Factor-1 (TGF-1), and Interferon (INF) production, in order to combat chronic fatigue syndrome." (PMID 35736467, 2022). "Other studies reported increased gene expression of IL-10, but not IL-6 or TNF, up to 48 h after a 25-min cycling exercise in FMS comorbid with chronic fatigue syndrome, but no change in patients with FMS only." (PMID 27296860, 2016). "In addition, there are reports that MCP-1 can be elevated without significant increase in other cytokines such as Il-6 in various situations such as SARS CoV-2 infection of septic patients and chronic fatigue syndrome." (PMID 40068933, 2025). "Moreover, even in populations with inflammatory background, such as chronic fatigue syndrome and SLE, IL-6 was found to have protective rather than disturbing effects on cognition." (PMID 30546293, 2018).
dilated cardiomyopathy (18 papers, 2012 to 2025). Cardiomyopathy which is characterized by dilation and contractile dysfunction of the left and right ventricles. "In support of this, high levels of plasma IFNγ, TNFα, (IL-1β), and IL-6 correlated with the severity of dilated cardiomyopathy in chagasic patients, indicating that exacerbated immune can cause local damage." (PMID 29867974, 2018). "Clinical studies have shown that HMGB1 and its associated inflammatory cytokines (IL-6, TNF-α) may be involved in the pathophysiological processes of dilated cardiomyopathy and accelerated heart function decline." (PMID 35571117, 2022). "In particular, beta-blocker initiation led to a decrease in circulating TNFα in patients with dilated cardiomyopathy, whereas a higher dose of ACE-I reduced circulating Interleukin-6 in individuals with chronic congestive heart failure more than a lower dose." (PMID 37108628, 2023). "A meta-analysis evaluating the effects of pentoxifylline on pro-inflammatory cytokines in patients with dilated cardiomyopathy of various causes (ischemic, idiopathic, and hypertensive) showed a significant reduction in plasma TNF-α concentrations and no change in IL-6 levels." (PMID 41066529, 2025).
gastric adenocarcinoma (18 papers, 2007 to 2026). "A retrospective Taiwanese study in operable gastric adenocarcinoma patients found IL-6 to be an independent prognostic factor for OS, although patients were treated between 1999 and 2002, prior to the widespread adoption of perioperative chemotherapy." (PMID 41249451, 2026). "The findings revealed that the expression of NFKB1 and HIF1A genes was significantly high, and IL-6 expressed the same between the stomach adenocarcinoma tissues compared to normal tissues." (PMID 39816318, 2024). "Another group investigated the response of human gastric adenocarcinoma cells to 44-nm polystyrene particles and found upregulation of IL-6 and IL-8." (PMID 39872873, 2023). "A persistent stomach infection with H. pylori induces secretion of proinflammatory cytokines, including IL-1β, IL-6, IL-8, and TNF-α, which are closely linked to MALT-lymphoma and gastric adenocarcinoma." (PMID 30646625, 2019). "We first compared the IL-6 mRNA expression in publicly available datasets from healthy stomach samples (n=174, GTEx) and tumor samples (n=414, TCGA-stomach adenocarcinoma) and showed that IL-6 expression was significantly enhanced in tumor tissues (P ≤ 0.0001)." (PMID 38422751, 2024). "No mutations have been detected in key positions of glycoprotein 130 (gp130) in human gastric adenocarcinoma samples; however, gp130 activation may occur due to increased expression levels of the IL-6 and IL-11 cytokines, which have potential as valuable biomarkers." (PMID 25788990, 2015). "A prospective, non-randomized study comparing RCS (n = 30) and LCS surgery (n = 120) for early gastric adenocarcinoma reported a lower postoperative CRP and interleukin-6 response in the LCS group." (PMID 34022914, 2021). "The study analysed the mRNA expression levels of ALB, BCL-2, NFKB1, HIF1A, and IL-6 in 408 stomach adenocarcinoma samples alongside non-tumour gastric tissues." (PMID 39816318, 2024). "Similarly, overexpressing NEIL2 in human gastric adenocarcinoma, AGS cells infected with the human coronavirus 229E strain significantly decreased IL6 transcript levels, concomitant with decreased expression of viral E-gene, when compared with control cells." (PMID 38071370, 2023). "One study performed a retrospective analysis of bazedoxifene, an inhibitor of the IL-6/IL-6R/GP130 complex, in patients with pancreatic (n = 5) or gastric adenocarcinoma (n = 2), showing biological tumor marker reduction in 80% and disease regression on PET-CT in 60% of cases." (PMID 34138876, 2021). "While IL-6 can induce miR-23a in hepatocytes, and miR-23a targets IL-6R in gastric adenocarcinoma cells, to our knowledge, there is no information regarding the regulation of IL-6 by miR-23a." (PMID 24143215, 2013).
idiopathic multicentric Castleman disease (18 papers, 2018 to 2026). "Idiopathic multicentric Castleman disease (iMCD) is a rare polyclonal lymphoproliferative disease caused by the overrepresentation of interleukin-6 (IL-6)." (PMID 34533616, 2021). "The principal cytokine responsible for causing idiopathic multicentric Castleman disease (IMCD) is interleukin-6 (IL-6)." (PMID 32766009, 2020). "Idiopathic multicentric Castleman disease (iMCD) is a chronic systemic inflammatory disease characterized by the production of interleukin (IL)-6." (PMID 39944226, 2025). "According to current guidelines and consensus, targeting IL-6 is the preferred first-line treatment for newly diagnosed idiopathic multicentric Castleman’s disease (iMCD)." (PMID 39650164, 2024). "Idiopathic multicentric Castleman disease (iMCD) is a systemic and polyclonal lymphoproliferative disease involving multiple organs, including the kidneys, due to the overproduction of interleukin-6 (IL-6)." (PMID 36698794, 2023). "Elevated serum IL-6 levels are largely found in patients with idiopathic multicentric Castleman disease." (PMID 34208103, 2021). "We used Siltuximab — an FDA-approved anti-IL-6 mAb under the brand name of Sylvant for the treatment of patients with idiopathic multicentric Castleman’s disease (iMAD) — as a control." (PMID 35126375, 2021). "However, high IL-6 levels are observed in idiopathic multicentric Castleman disease (iMCD), a rare hyperinflammatory disorder involving polyclonal lymphoproliferation." (PMID 35928820, 2022). "Considering the downstream effect of IL-6 on hepatocyte stimulation, serum CRP concentration is seen as a biomarker of disease activity in idiopathic multicentric Castleman disease." (PMID 34208103, 2021). "Recent advancements in the treatment of idiopathic multicentric Castleman disease (iMCD) have pointed to the efficacy of sirolimus, an mTOR inhibitor, particularly in cases that have not responded to traditional IL-6 inhibitors." (PMID 38927348, 2024). "Interleukin 6 (IL-6) inhibitors are the first-line treatment for idiopathic multicentric Castleman disease (iMCD); however, there is no established treatment for cases that are resistant to IL-6 inhibitors." (PMID 33327255, 2020). "Since IL-6 was not over-expressed in tissue of idiopathic multicentric Castleman's disease, IL-6 may be produced outside the affected organs, and circulating IL-6 may lead to lymphoplasmacytosis at nodal and extranodal sites." (PMID 29467920, 2018).
intrahepatic cholangiocarcinoma (18 papers, 2017 to 2025). A carcinoma that arises from the intrahepatic bile duct epithelium in any site of the intrahepatic biliary tree. "IL‐6 induces cGGNBP2 expression in intrahepatic cholangiocarcinoma (ICC), which encodes a cGGNBP2‐184aa protein." (PMID 40356340, 2025). "In human intrahepatic cholangiocarcinoma, vascular‐derived vCAFs have been found to be strongly associated with tumour cells through the IL‐6/IL‐6R axis, which not only promote the occurrence of tumours but also further mediate their progression and invasion." (PMID 38158643, 2024). "In intrahepatic cholangiocarcinoma (ICC), IL-6 increases the expression of circRNA GGNBP2 to encode the protein cGGNBP2-184aa, which in turn forms a positive feedback loop of IL-6/cGGNBP2-184aa/STAT3 to facilitate ICC progression." (PMID 38890694, 2024). "Moreover, vCAFs promoted the occurrence and development of intrahepatic cholangiocarcinoma through the IL‐6/IL‐6R signalling pathway and promoted the dry nature of tumour cells." (PMID 38158643, 2024). "IL-6 induced programmed death ligand 1 expression through the mTOR pathway in intrahepatic cholangiocarcinoma, suggesting that IL-6 antibodies may help to overcome resistance to immune checkpoint inhibitors in intrahepatic cholangiocarcinoma." (PMID 38689325, 2024). "IL-6 secreted by vascular CAFs could promote tumor cell stemness in intrahepatic cholangiocarcinoma." (PMID 37033924, 2023). "IL-6 is proposed to be secreted from CAFs of this tumour, inducing epigenetic changes in cholangiocytes and thereby enforcing a malignant transformation driving the initiation of intrahepatic cholangiocarcinoma." (PMID 34047814, 2021). "FXR inhibited intrahepatic cholangiocarcinoma aggressiveness through the suppression of IL-6." (PMID 34047814, 2021). "Studies have shown that in intrahepatic cholangiocarcinoma (ICC) cells, IL-6 induces the expression of cyclic RNA (circRNA) GGNBP2 (cGGNBP2)." (PMID 39906665, 2024). "For instance, the biogenesis of circRNA GGNBP2 (cGGNBP2) was mediated by IL-6/STAT3 pathway activation, and IL-6/cGGNBP2-184aa (a protein encoded by cGGNBP2)/STAT3 formed a positive feedback loop to promote tumor progression for intrahepatic cholangiocarcinoma." (PMID 37264406, 2023). "In a desmoplastic intrahepatic cholangiocarcinoma (ICC) mouse model, cancer-associated fibroblasts (CAFs) recruited CD33+ MDSCs to the tumor and also mediated hyperactivation of 5LO metabolism in the MDSCs through CAF-derived IL-6 and IL-33." (PMID 38786066, 2024). "The results of the study showed that CAF increased the expression and activity of 5-lipoxygenase (5-LO) in MDSCs by secreting IL-6 and IL-33, which greatly contributed to the efficiency of tumor sphere formation and stemness marker gene expression in intrahepatic cholangiocarcinoma (ICC) cells." (PMID 37007004, 2023). "However, a recent report observed a negative correlation between IL-6 levels and intrahepatic cholangiocarcinoma." (PMID 34047814, 2021).
lipodystrophy (18 papers, 2006 to 2025). A congenital or acquired disorder characterized by abnormal loss or redistribution of the adipose tissue in the body. "Baseline factors associated with more severe lipodystrophy (lipoatrophy, baseline tNRTI, raised IL6, and glucose) predicted greater limb fat recovery at 96 weeks." (PMID 22046394, 2011). "Albeit interferons and IL-6 are necessary for early adipocyte development, the excessive production of interferons and IL-6 may either cause a cachectic loss of fat mass—lipodystrophy—or aggravate metabolic inflammation." (PMID 37830559, 2023). "Furthermore, AT inhibited lipodystrophy-associated increase of plaque macrophage infiltration and aortic expression of proinflammatory cytokines (Mcp-1, Il-1β, and Il-6) in Seipin/Apoe dKO mice, as shown by CD68 immunohistochemical staining and real-time quantitative PCR analysis, respectively." (PMID 38525541, 2024). "The finding in this study that higher IL-6 levels at baseline was associated with greater fat gain over 96 weeks, is consistent with results from these previous studies suggesting that high IL-6 may represent those participants with lipodystrophy at baseline." (PMID 22046394, 2011). "ART, particularly protease inhibitors, exacerbates these issues by inducing lipodystrophy and increasing the production of inflammatory cytokines such as IL-6 and TNF-α." (PMID 39339002, 2024). "Age had the strongest positive association with lipodystrophy and also positively correlated with several inflammatory markers, including LBP, CRP, IL-6, ICAM-1, and serum amyloid A (SAA)." (PMID 34006628, 2021). "Though, in order to deepen our studies on the inflammatory profile of lipodystrophy we analyzed the plasma levels of cytokines involved in the development of IR such as IL-1β, IL-6 e TNF-α." (PMID 29449893, 2018). "IL-6 mRNA expression has also been shown to increase in peripheral adipocytes in HIV treated participants with lipodystrophy." (PMID 22046394, 2011). "Some studies demonstrated high IL-6 to be correlated with limb fat in HIV patients with lipodystrophy, whereas others have only demonstrated the same in HIV positive patients compared with controls, not those with lipodystrophy." (PMID 22046394, 2011). "Furthermore, gene expression analysis showed that ibuprofen remarkably decreased the expression of Mcp1 and IL-6 in the lipodystrophy group." (PMID 38989000, 2024). "Of note, MR is a trigger of IL6 expression, a main determinant of LMNA-linked lipodystrophy." (PMID 37998321, 2023). "Moreover, it has recently been demonstrated in individuals with lipodystrophy that WC is associated with IFN-γ and IL-6, which are cytokines that have been implicated in the pathogenesis of NAFLD." (PMID 37679847, 2023). "In addition, IL-6 and TNF-α stimulates the hepatic lipogenesis and were also associated with lipodystrophy in HIV patients." (PMID 29997625, 2018). "Although preliminary, the authors speculated that lipodystrophy could be a result of elevated secretion of inflammatory cytokines IL-6 (interleukin-6) and TNFα." (PMID 25195639, 2014). "In addition, IL-6 induces lipodystrophy that likely favors the release of pathogens from AT into the circulation and, as a consequence, the induction of relapses." (PMID 24835240, 2014). "Importantly, IL-6, and to a lesser extent IL-1β, have been linked to HIV lipodystrophy." (PMID 34383714, 2021). "This process is known to be enhanced by increased levels of tumor necrosis factor, interleukin 6 (IL-6), and hydroxycorticosteroids present in many patients with HIV lipodystrophy." (PMID 22046183, 2011). "In contrast, IL-6 or suPAR levels were not changed in lipodystrophy, but tended to be higher in HIV-infected patients than Controls." (PMID 26244048, 2015). "IL-6 and suPAR levels were not altered in lipodystrophy of either subtype, in agreement with most studies." (PMID 26244048, 2015).
lipodystrophy (continued). "Similarly, elevated circulating and mRNA levels of TNFα, IL-6 and MCP-1 in WAT and brown adipose tissue were found in a transgenic mouse model overexpressing nSREBP1c (nuclear SREBP1c) that mimics lipodystrophy." (PMID 25195639, 2014). "IL-6 is elevated in HIV, but IL-6 levels appear not to be affected in lipodystrophy." (PMID 26244048, 2015). "How IL-6 reflects and affects AT and muscle mass in HIV-infection and lipodystrophy is not clear." (PMID 26244048, 2015).